GPR50 (G protein-coupled receptor 50)
Diseases named in the same sentence as GPR50 in open-access papers (continued):
Sharing a sentence is not in itself a finding about the gene and the disease.
cancer (7 papers, 2018 to 2026). A tumor composed of atypical neoplastic, often pleomorphic cells that invade other tissues. "This correlation highlights GPR50 as a diagnostic tool and its potential use as a therapeutic target for cancer." (PMID 36769125, 2023). "As GPR50 knockdown attenuated cancer progression, we attempted to uncover the underlying signaling mechanism." (PMID 32405532, 2020). "Moreover, we analyzed the association between prognosis and GPR50 expression in various cancer patients using The Cancer Genome Atlas (TCGA) database via the SurvExpress web." (PMID 32405532, 2020). "GPR50 plays roles in various physiological processes, including cancer progression, Notch signaling, and insulin, leptin, and glucocorticoid signaling." (PMID 41666959, 2026). "The relevance of GPR50 in cancer cell progression has been demonstrated in this and previous studies." (PMID 36769125, 2023). "We examined that the knockdown of GPR50 in CSLC led to decreased cancer properties, such as sphere formation, cell proliferation, migration, and stemness." (PMID 36769125, 2023). "By comparing the genes (COL1A1, PDL2) involved in cancer cell progression, the expression level of GPR50 was found to be upregulated in CSLC." (PMID 36769125, 2023). "Herein, we confirmed that the expression of G protein-coupled receptor 50 (GPR50) in cancer stem-like cells (CSLC) is higher than that in other cancer cells." (PMID 36769125, 2023). "Studies have been conducted to prevent cancer development through GPR50 signaling of the TGF-β receptor." (PMID 36769125, 2023). "Subsequently, we analyzed GPR50 mRNA expression in these cancers using several Gene Expression Omnibus (GEO) datasets." (PMID 32405532, 2020). "Here, we investigated the expression patterns of GPR50 in various cancer cells and found dysregulated GRP50 expression." (PMID 32405532, 2020). "Overall, these results indicate that GPR50 expression is dysregulated in various cancers and specifically upregulated in HCC." (PMID 32405532, 2020). "This describes a previously unappreciated spontaneous TGFβ-independent activation mode of TβRI and identifies GPR50 as a TβRI co-receptor with potential impact on cancer development." (PMID 29572483, 2018). "Hence, GPR50-cAMP signaling pathway is a promising cancer drug target and screening ligands for GPR50 is of great importance." (PMID 35694242, 2022). "In addition, our previous study was given a clue that several GPCRs, including GPR50, are involved in the reprogramming of somatic cells to cancer stem cells and in the maintenance of stemness function." (PMID 32405532, 2020). "Here, we show that G-protein-coupled receptor 50 (GPR50) in HCC is overexpressed and that GPR50 knockdown may downregulate cancer cell progression through attenuation of the Notch signaling pathway." (PMID 32405532, 2020). "Available data in human cancer data bases indicated that GPR50 underexpression and not overexpression is associated with cancer development and poor survival prognosis indicating that GPR50 predominantly acts as a tumor suppressor." (PMID 29572483, 2018). "Among them, six melatonergic genes were significant unfavorable factors in cancers (e.g., MTNR1A in ESCA and LIHC; GPR50 in KIRC, LIHC, and STAD; NQO2 in BRCA, LIHC, and LUSC; CYP1B1 in KIRC and STAD; ASMT in ESCA, HNSC, and LUAD; and MTNR1B in STAD)." (PMID 33842355, 2021). "Strikingly, GPR50 had the highest expression level in the metastatic group compared to that in the non-metastatic group in three cancer types (e.g., BRCA, COAD, and LUAD)." (PMID 33842355, 2021). "We also found that GPR50 knockdown attenuates cell proliferation, sphere formation, migration, and drug resistance of HCC cells, whereas overexpression of GPR50 upregulates cancer properties in hepatocytes, strongly supporting an oncogenic function for GPR50 in HCCs." (PMID 32405532, 2020). "The part of GPR50 that regulates the overall signaling of cancer stem cells is not yet clear." (PMID 36769125, 2023).
tumor (5 papers, 2018 to 2024). "This ectopic expression of GPR50 protects against tumor development, and its absence is evident in pro-tumorigenic animal models." (PMID 36769125, 2023). "It has been reported that GPR50 can make a heterodimer with type I TGFβ receptor (TβRI) to lower the tumor growth in the human breast by activating the antiproliferative effect of the TGFβ receptor." (PMID 36769125, 2023). "Collectively, these results show that endogenous GPR50 has anti-proliferative effects, like TGFβ, and has protective effects against tumor development in the MMTV/Neu model." (PMID 29572483, 2018). "The effect of GPR50 overexpression on the tumor-promoting capacity of MDA-MB-231 cells was then studied in xenograft experiments." (PMID 29572483, 2018). "Ectopic expression of GPR50 protects against tumor development and its absence is pro-tumorigenic in animal models." (PMID 29572483, 2018). "GPR50 overexpression in MDA-MB-231 cells mimics the anti-proliferative effect of TβRI and decreases tumor growth in a xenograft mouse model." (PMID 29572483, 2018). "In line with the TGFβ-like behavior of GPR50, ectopic expression of GPR50 in MDA-MB-231 inhibits cellular proliferation in a TβRI-dependent manner, and tumor development in xenograft model." (PMID 29572483, 2018). "Using the tumor-related Gi-coupled GPCR (GPR50) signaling pathway as a model, our G-Flamp2 living cell imaging experiments demonstrated that adipose tissue extract activated the orphan GPCR GPR50." (PMID 35694242, 2022). "No tumors expressed GPR50 in this study, however, considering the potential role of MTNR1A in tumor suppression based on previous research, future studies investigating GPR50 may be of value." (PMID 39201396, 2024).
neurodegenerative disease (2 papers, 2020 to 2024). A disorder of the central nervous system characterized by gradual and progressive loss of neural tissue and neurologic function. "Although the importance of GPR50 and ligand interactions has been established for neurodegenerative diseases, further research is needed to clarify downstream signaling pathways." (PMID 38895631, 2024). "Although there is a potential link between GPR50 and psychiatric conditions and given the overlap between psychiatric and neurological disorders, recent findings have addressed the role of GPR50 in neurodegenerative diseases." (PMID 38895631, 2024). "Changes in these receptors' expression patterns may contribute to the development and progression of the disease, pointing to a possible link between GPR50-related melatonin signaling pathways and neurodegenerative diseases like AD." (PMID 38895631, 2024). "These enriched TFs displayed maximum interactions with their target genes (GPR50, ABCC9, ZNF667 and CALB1) and could prove relevant to several neurodegenerative diseases." (PMID 32967368, 2020).
GPR50 also shares sentences with these, for which no sentence is quoted: Alzheimer disease (1 paper); amyotrophic lateral sclerosis (1); autism (1); autism spectrum disorder (1); brain disorder (1); emotional dysregulation (1); epilepsy (1); gastric carcinoma (1); growth disorders (1); inflammation (1); intellectual disability and (1); invasive lobular breast carcinoma (1); metabolic disorders (1); neurological disorders (1); Parkinson disease (1); pituitary hormone deficiencies (1); schizophrenia (1); Sepsis (1); Simpson-Golabi-Behmel syndrome (1).